CCL2 (C-C motif chemokine ligand 2)
Diseases named in the same sentence as CCL2 in open-access papers (continued):
Sharing a sentence is not in itself a finding about the gene and the disease.
tumor (continued). "Chemokines such as CSF1 and CCL2 secreted by tumor cells can recruit monocytes from peripheral circulating blood to the tumor microenvironment (TME), and then monocytes differentiate into macrophage." (PMID 36313679, 2022). "The activation of hypoxia signaling increases the expression of adipokines, especially the pro-inflammation adipokines (including CCL2, CXCL8, CXCL10, IL-18, IL-1α and Oncostatin M), which is involved in the recruitment of tumor-associated immune cells." (PMID 35350384, 2022). "CCL2 can be secreted by tumor cells and multiple cell types, mediating the formation of the tumor-promoting and immunosuppressive microenvironment to promote cancer development, progression, and anticancer drug resistance." (PMID 36077785, 2022). "Th17 cells are generated by tumor-derived IL1β and IL13, and accumulate in tumor tissues in response to various chemokines, including CCL2, CCL5, CCL20, CCL17, CCL22, and MIF, which are produced from tumor cells." (PMID 36211375, 2022). "The role of the proinflammatory chemokines MIP1-α (CCL3), MIP1-β (CCL4), and MCP-1 (CCL2) in the tumor remains controversial." (PMID 35359980, 2022). "Anti‐CCL2 antibodies selectively inhibit radiotherapy‐dependent monocyte/macrophage recruitment and retard tumor growth when used in combination with radiotherapy." (PMID 35702353, 2022). "Results showed that the combined treatment of OAT-1746 and anti-PD-1 antibody reduced tumor growth by decreasing levels of CCL2 and CCL5 in the blood plasma of mouse." (PMID 36091114, 2022). "In tumor-bearing host, myeloid cells are recruited to tumor sites by chemokines produced by the tumor, such as CCL2 and CCL518,19." (PMID 36104342, 2022). "Taken together, these results suggest that bone marrow-derived CCR2+/CX3CR1+ cells from naïve and tumor-bearing animals migrate to CCL2 and CCL7, in a CCR2-dependent manner." (PMID 36685592, 2022). "This highlights the role of the CCL2/CCR2 axis in the tumor microenvironment in stimulating PCa expansion and metastasis." (PMID 35406450, 2022). "The secretome of MSCs is variable but mostly CCL2, CCL5, IL-6, TGFβ, VEGF which have been implicated in tumor growth and/or metastasis are commonly expressed." (PMID 35150338, 2022). "ATC-like tumor shows high levels of T cell infiltration, chemo-cytokines (CCL2, CCL3, CCL4, CCL5, CXCL9, and CXCL10), and immune checkpoints." (PMID 36293435, 2022). "M-MDSCs and monocytes are mainly recruited by chemokines produced by tumor cells, including CCL2, CCL5, and CSF1." (PMID 35122833, 2022). "Microglia/macrophages are recruited by GBM release of CCL-2 (macrophage chemoattractant protein-1) to promote the tumor invasiveness." (PMID 36048342, 2022). "Mice lacking in FBXW7 show improved expression of chemokine C-C Motif Chemokine Ligand 2 (CCL2) in serum, which contributed to the recruitment of macrophages and monocytic myeloid-derived cells and then led to the metastasis of tumor." (PMID 35814468, 2022). "These correlations change with time, with early low expression of CCL17, CXCL1 and CCL2 eventually promoting myeloid cell development that maintains/promotes larger tumours." (PMID 35226704, 2022). "CXCL5 and CCL2 released by macrophages in the tumor microenvironment can enhance tumor metastasis by interacting with their respective receptors in tumor cells." (PMID 36477408, 2022). "Multiple preclinical murine models have demonstrated the potent efficacy of CCR2 inhibitors and anti-CCL2 antibodies in reducing tumor growth and metastasis." (PMID 36679900, 2022). "Monocytes have been considered as the precursors of TAMs for many years since CCL2/CCR2 signaling which recruits monocytes from bone marrow to tumor facilitates breast cancer metastasis." (PMID 36035994, 2022). "Low levels of CCL-2 promote tumor growth, and high levels of CCL-2 cause a large number of macrophages to accumulate and tumor destruction." (PMID 36081554, 2022).
tumor (continued). "Remarkably, we observed clear induction in the expression of marker genes of inflammatory progenitor cells after treatment with tumor cell-conditioned medium, including CCL2, CXCL2, TNFAIP6, and TNFRSFL12a." (PMID 36376273, 2022). "The results derived from CCLE database analysis also displayed a significant difference in the expression of CCL2 between tumor cells with high or low MTA1 levels." (PMID 35350571, 2022). "The vital role of CCL2 in facilitating tumor metastasis has been demonstrated in diverse cancers, which involve the activation of multiple signaling pathways, including the MAPK, JAK/STAT, and PI3K/AKT pathways." (PMID 36077785, 2022). "Among BALB/c mice, the highest CCL2 concentrations were observed in 67NR tumor-bearing (1000 IU and 1000 IU+cal) and healthy (100 IU+cal) mice." (PMID 36230508, 2022). "The blockade of CCL2 alone showed a slowing in the overall fold change in tumor volume (~ threefold) compared to a saline control twelve days after the initiation of treatment." (PMID 35461243, 2022). "Our own work suggests that these monocytes are only recruited into the tumor microenvironment if the tumor cells can produce and release monocyte specific chemokines such as CCL2." (PMID 35906202, 2022). "Many effector cells then travel through the bloodstream to the tumor site by involving various chemokines (e.g., C-C motif chemokine ligand 2 (CCL2), C-X-C motif chemokine ligand 2 (CXCL2), and C-X-C motif chemokine ligand 16 (CXCL16))." (PMID 35456701, 2022). "CC chemokine ligand-2 (CCL2), a proinflammatory chemokine that mediates chemotaxis of multiple immune cells, plays a crucial role in the tumor microenvironment (TME) and promotes tumorigenesis and development." (PMID 36077785, 2022). "It has been shown that mast cells can induce further tumor cell invasion by regulating EMT via the ERβ/CCL2/CCR2 signaling axis (Erβ, estrogen receptor β)." (PMID 36611857, 2022). "CCL2 overexpression significantly protected the tumor cells from trastuzumab treatment, elevated the half inhibitory concentration (IC50) of trastuzumab and promoted the resistance in NCI-N87 and KATO III cells via a paracrine effect on TAMs." (PMID 35851310, 2022). "CCL2 was a highly expressed cytokine in HNSCC cells under the serum-deficient condition, indicating that tumor cells were an important cellular source of CCL2 in the tumor microenvironment." (PMID 35177591, 2022). "ACKR2–/– mice have been demonstrated to have increased killing activity of NK cells through enhanced CCR2 expression and NK infiltration into the CCL2-expressing melanoma tumor microenvironment." (PMID 35677043, 2022). "In gastric cancer, TG2 upregulation was shown to enhance inflammation and promote tumor growth by recruiting macrophages to the tumor milieu via Il-1β-mediated induction of CCL2 and CXCL10." (PMID 35681474, 2022). "To further explore this possibility, we tested the effects of Bag3 on the expression of the LITAF target CCL2, which plays a major role in tumor development." (PMID 36077705, 2022). "Knockdown of CCL2 in tumor cell lines remarkably impairs tumorigenesis with downregulation of TAM infiltration." (PMID 35873458, 2022). "Deeper insight into the potential mechanisms of the CCL2/CCR2 axis in tumor progression and treatment will provide new directions for a better understanding of malignancies." (PMID 35702353, 2022). "Another study showed that the blockade of CCL2 binding to its receptor CCR2 on macrophages or depletion of CCL2 decreased monocyte recruitment and prolonged tumor survival in mice." (PMID 35740975, 2022). "In a preclinical pancreatic ductal adenocarcinoma model, the inhibition of CCL2 in isolation had little impact on tumor growth unless used in combination with radiotherapy." (PMID 36249052, 2022). "We observed that the surface of tumor cells exhibited more numerous and longer filopodia after treatment with CCL2 for 2 hs." (PMID 35177591, 2022).
tumor (continued). "We confirmed that Cxcl1 and Ccl2 were the two mediators present in tumour conditioned medium of GK1 cells." (PMID 35170261, 2022). "Taken together, the CCL2/CCR2 signaling axis is involved in a wide range of tumor cell activities, and regulation of CCL2 and/or CCR2 expression influences tumor progression." (PMID 35702353, 2022). "Recent works demonstrated that standard care of treatment for several tumors determine a release of bioactive factors, such as VCAM1 and CCL2, that are involved in the increased macrophages infiltration in the tumor microenvironment." (PMID 35757002, 2022). "CCL2, an important cytokine for macrophage chemotaxis and activation, is also produced by many types of tumor cells." (PMID 36547079, 2022). "It is responsible for silencing both MHC-I and CCL2, masking tumor cells from both the innate and adaptive arms of the immune system." (PMID 36509828, 2022). "Cancer-associated fibroblasts play important roles in tumor growth and maintenance through secreting autocrine and paracrine signaling molecules such as IL-1α, IL-1β, IL-6, IL-33, HGF, VEGF, TNF-α, TGF-β, CCL-2, CXCL-12, CXCR-4, MMP-2, and Snail." (PMID 35992863, 2022). "The pivotal role of CCL2 is its ability to trigger invasive phenotypes of cancer cells and recruit monocytes to tumor sites." (PMID 35408440, 2022). "GAMs are actively recruited into the tumour core through CCL2, SDF-1, M-CSF and GM-CSF signalling, and undergo further polarisation to promote a pro-tumorigenic environment." (PMID 36430641, 2022). "Nitration of CCL2 (N-CCL2) through reactive nitrogen species within the tumor was shown to decrease its affinity to the receptor CCR2." (PMID 36366354, 2022). "This shows that the addition of anti-CCL2 to 5-FU slowed the fold-change (change from the original measurement to the final measurement) in tumor volume from Day 0 to Day 12 (~ 5 fold)." (PMID 35461243, 2022). "The capacity of MSCs to move toward tumor tissue is also mediated by other factors, such as chemokines CCL2, CCL5, CXCL16, diffusible cytokine IL-8, as well as growth factors IGF1, PDGF, VEGF, and TGF-β." (PMID 36324128, 2022). "CCL2 knockout or autophagy induction successfully reverses the drug resistance of tumor cells, which have potential value in biomarkers and intervention targets of chemotherapy resistance." (PMID 35321506, 2022). "CCL2 can decrease drug‐induced cytotoxicity to support tumour cell growth by inhibiting proapoptotic autophagy and is regarded as an intervention target for chemotherapy resistance." (PMID 34464477, 2021). "For example, in hepatocellular carcinoma, inhibition of CCL2 with specific monoclonal antibodies slows tumor progression and metastasis by blocking the recruitment of TAMs." (PMID 34178692, 2021). "TAMs of hematopoietic origin are recruited locally to the TME from peripheral blood monocytes and are polarized into TAMs via tumor-derived M-CSF, CCL2, and SDF-1." (PMID 34884995, 2021). "CCL2 was considered the leading chemokine expressed by various tumor cells and exerts a pivotal function in immune cell recruitment, especially TAMs." (PMID 34580284, 2021). "The origin of elevated levels of circulating CCL2 is likely to be tumour derived, as our study finds significantly elevated levels of CCL2 in tumour lysates prepared from wildtype mice." (PMID 33494138, 2021). "In a ccRCC xenograft model, the binding of VEGF to VEGFR-1 prompted tumor cells to secrete CCL2, which mediated the infiltration of TAMs." (PMID 33746989, 2021). "Studies have shown that CCL2 in the tumor microenvironment promotes the progression and metastasis of different tumors, including BC." (PMID 34185683, 2021). "The CCL2/CCR2 signaling axis plays a central role in regulating the infiltration of circulating monocytes into the tumor microenvironment, making it a promising TAM-targeting therapy." (PMID 34201127, 2021).
tumor (continued). "Investigations using multiple metastatic models have provided evidence that neutrophils entrained by CCL2-expressing tumor cells are capable of attenuating lung metastases." (PMID 34386431, 2021). "It was demonstrated in a rat model of GBM that the inhibition of CCL2 led to the blockade of macrophage recruitment and inhibition of angiogenesis, resulting in decreased tumor volume in CCL2-expressing GBM tissues." (PMID 34200145, 2021). "Carlumab is a CCL2-targeted antibody, and it successfully represses macrophage infiltration and tumor growth." (PMID 35008832, 2021). "We show that IBC tumors mobilize distinct subsets of inflammatory cells locally and systemically, and demonstrate a key role of CCL2 secreted at very high levels in recruiting macrophages into tumors and thereby facilitating tumor growth and metastasis." (PMID 34824220, 2021). "CHI3L1 can promote tumor progression by upregulation of pro‐inflammatory mediators, like CCL2, CXCL2, and MMP‐9." (PMID 33626234, 2021). "Targeting CCL2 with bindarit induces tumour regression, which has been confirmed in some preclinical studies." (PMID 34464477, 2021). "In line with this, in the CCL2-null H22 tumor model, EE still had a tumor protective effect, which was abrogated after blockade of the host CCL2 signaling with CCL2 neutralized antibody." (PMID 34593796, 2021). "CCL2 released by CAFs and tumour cells recruits myeloid-derived suppressor cells (MDSCs) and macrophages." (PMID 34059019, 2021). "CSF-1 has been described as the most important tumor-derived factor leading to monocyte recruitment through CCL2/CCR2 interaction, so CCR2 blockade therapies have been effective in suppressing TAM recruitment." (PMID 34209703, 2021). "The effective dose of DIM reversed the upregulation of the expression of CCL-2, IL-6, and IL-8 in GC-MSCs by β-TrCP-mediated iκBα degradation and NFκB signaling pathway activation, thereby enhancing tumor progression." (PMID 33842314, 2021). "To examine the systemic effects of CCL2 downregulation, we examined the lungs of A3250 tumor-bearing mice during the early stages of tumor dissemination by immunostaining (3–4 weeks post-injection)." (PMID 34824220, 2021). "In their model, enhanced production of CCL2 in the tumor tissue induced by 3M-052 played important roles for the antitumor effect, whereas both type I IFNs and IFN-γ contributed only partially to the antitumor effect." (PMID 34439104, 2021). "Tumor antigens can reprogram inflammatory cells and promote tumor immune invasion via NF-κB-induced CCL2 production." (PMID 34386431, 2021). "The diverse mechanisms by which CCL2 regulates the tumor immune microenvironment are precisely regulated by tumor cells, tumor-infiltrating immune cells, and the tumor stroma." (PMID 34386431, 2021). "CCL2 can be produced by multiple cell types in the tumor environment, while CCR2 can also be expressed by multiple cell types including tumor cells." (PMID 34804061, 2021). "Bindarit is an anti‐inflammatory indazole derivative that can inhibit the synthesis of CCL2, with a potential inhibitory function in tumour development." (PMID 34464477, 2021). "Flow cytometry analysis further revealed that blocking CCL2 in SE mice mimicked the effect of EE-mediated reshaping of the tumor microenvironment, that is, an increase of CD8+ T cells and M1-like TAMs and a decrease of G-MDSCs and M2-like TAM." (PMID 34593796, 2021). "CCL2 secreted by TAMs also contributes to the recruitment of monocytes/macrophages to the hypoxic tumor area." (PMID 33230600, 2021). "Here the authors report the characterization of a human IBC cell line recapitulating the clinical and histopathological features of the human disease, and implicating its high level of CCL2 in macrophage infiltration and tumor progression." (PMID 34824220, 2021). "Significantly high CCL2 expression levels have been detected in the epithelial regions of many tumor types." (PMID 34917508, 2021).
tumor (continued). "The monocyte infiltration and proinflammatory signaling are supported via pro-inflammatory cytokines and chemokines (ex., CCL2) from the tumor microenvironment increased blood vessel wall permeability and signaling from dead and damaged cancer cells." (PMID 33800829, 2021). "As shown, the proportion of MDSCs (CD45+/CD11b+/Gr1+) were lower in CCL2−/− mice model after tumor injection, suggesting the CCL2 expression is correlated with BC proliferation and motility." (PMID 34249913, 2021). "Macrophages are attracted to the circulation by various agents released from tumor cells, including CSF-1, CCL-2, VEGF, TNFα, or TGFβ, and accumulate at pre-metastatic sites." (PMID 33919517, 2021). "Release of proinflammatory CXCL10 and CCL2 by macrophages is stimulated by the contact with tumor cells, which accelerates cancer cell recruitment to and growth within bone as well as osteoclastogenesis." (PMID 34064859, 2021). "CCL2 released from tumor cells after platelet stimulation is the ligand for chemokine receptor 2 (CCR2) expressed on monocytes and endothelial cells." (PMID 33937274, 2021). "While the increased expression of CCL2 by CAFs enhanced proliferation, invasion and metastasis, and HNSCC tumor growth, the use of specific CCL2 inhibitors significantly reduced tumor burden in vivo." (PMID 33925575, 2021). "The expression of CCL2 was upregulated 11.1-fold in tumor-adjacent tissue, and 5.3-fold in tumors compared to normal mucosa, in CCL7 2.3- and 1.9-fold, and in CCL8 8.3- and 2.1-fold." (PMID 34885960, 2021). "In this model, CAF-derived CCL2 signaling promoted tumor growth by enhancing the recruitment of MDSCs and supporting cancer immune evasion." (PMID 34681633, 2021). "In different cancers, crosstalk between TAMs and tumour cells play various roles in their growth through the CCL-2/CCR-2 axis." (PMID 34336101, 2021). "Our group previously discovered that the nitration of the inflammatory chemokine CCL2 limited T cell access into the tumor lesion by altering its chemoattractant properties." (PMID 34675917, 2021). "Accordingly, cells which were grown in serum-free medium and treated with a CCL2 neutralizing antibody or a CCR2 antagonist (RS504393) had significantly decreased proliferation of tumor cells compared with untreated control cells." (PMID 34804061, 2021). "The expression of CCL2 correlated with all of the other chemokines (also in tumor-adjacent tissue), while CCL19 was the least correlated gene." (PMID 34885960, 2021). "In concert with IL-6, CCL2 increases the survival of macrophages and stimulates their differentiation towards a tumor-promoting M2-like phenotype." (PMID 34064859, 2021). "Monocytes are recruited to the tumor by various growth factors and cytokines such as CCL2, CCL5, and CSF1." (PMID 34209703, 2021). "Hypoxia-induced ejection of CCL2-rich exosomes from tumor cells enhances oxidative phosphorylation in macrophages and tumor progression." (PMID 34386431, 2021). "CCL2 produced by tumor cells stimulates microglial IL-6 production, which leads to tumor growth and invasiveness." (PMID 34949203, 2021). "Classical monocytes recruited to tumor site by chemokines, including colony-stimulating factor 1 (CSF-1), chemokine (C-C motif) ligand 2 (CCL2), and chemokine (C-C motif) ligand 5 (CCL5), then polarized into M2 tumor-associated macrophages (TAMs)." (PMID 34141607, 2021). "FL-FDC crosstalk supports tumor growth and, through CCL2 and colony stimulating factor-1 (CSF-1) secretion, promotes monocyte recruitment, differentiation, and polarization toward the M2-like phenotype." (PMID 35008305, 2021). "Our findings suggest that in addition to controlling mechanical and thermal hypersensitivity, gabapentin also regulates tumor proliferation, CCL2 secretion, and calcium influx." (PMID 34575835, 2021).